IKBKB (inhibitor of nuclear factor kappa B kinase subunit beta)
Diseases named in the same sentence as IKBKB in open-access papers (continued):
Sharing a sentence is not in itself a finding about the gene and the disease.
breast carcinoma (continued). "The suppression of IKBKB through miR-16 sensitizes breast cancer cells to paclitaxel treatment." (PMID 31014274, 2019). "Furthermore, our results validated an inverse correlation between miR-16 expression and IKBKB expression in breast cancer tissues." (PMID 26993770, 2016). "Moreover, miR-16 was highly expressed in Taxol-sensitive breast cancer tissues compared with Taxol-resistant tissues, and there was an inverse correlation between miR-16 expression and IKBKB expression in breast cancer tissues." (PMID 26993770, 2016). "Since IKBKB plays a critical role in Taxol-induced cell cytotoxicity and apoptosis, we sought to determine whether miR-16 promoted the response of breast cancer cells to Taxol by suppressing IKBKB expression." (PMID 26993770, 2016). "In accordance with previous data, we identified IKBKB as a direct target of miR-16, overexpression of IKBKB could decrease Taxol-induced cytotoxicity and apoptosis in breast cancer cells." (PMID 26993770, 2016). "Therefore, we detected the expression of miR-16 and IKBKB in paraffin-embedded breast cancer samples by in situ hybridization (ISH) and immunohistochemical (IHC) analysis, respectively." (PMID 26993770, 2016). "Taken together, these results clearly demonstrate that miR-16 could sensitize breast cancer cells to Taxol at least partially through the direct suppression of IKBKB expression." (PMID 26993770, 2016). "Thus, targeting circRNA14052/miR-214-3p/IKBKB axis may be a promising approach for the treatment of breast cancer." (PMID 41044672, 2025). "Given the observed oncogenic effects of circRNA-14,052 and tumor-suppressive effects of miR-214-3p in breast cancer, we then performed rescue assays to investigate whether circRNA-14,052 promotes breast cancer progression by sponging miR-214-3p to regulate IKBKB expression." (PMID 41044672, 2025). "For example, expression of miR-16 was found to be downregulated in paclitaxel-resistant breast cancer cell lines, and exogenous overexpression of miR-16 sensitised breast cancer cells to Paclitaxel induced apoptosis and cytotoxicity via direct modulation of IκB kinase β (IKBKB)." (PMID 35582270, 2019). "Therefore, miR-16 sensitizes breast cancer cells to Taxol through the suppression of IKBKB expression, and it may potentially serve as a therapeutic target for overcoming Taxol resistance in human breast cancer." (PMID 26993770, 2016). "Importantly, we found that miR-16 contributed to Taxol chemosensitivity through the suppression of IKBKB expression, which partially explained miR-16-mediated Taxol cytotoxicity, indicating that the miR-16-IKBKB axis was involved in Taxol sensitivity in breast cancer cells." (PMID 26993770, 2016). "Taken together, these data indicate that miR-16 increases the chemosensitivity of breast cancer to Taxol through suppression of IKBKB expression, and combination of miR-16 targeted gene therapy and Taxol chemotherapy might represent a promising novel clinical strategy for human breast cancer." (PMID 26993770, 2016). "We used the STRING bioinformatic tool to find biological processes associated with the gene products that we analyzed for their prognostic impact on breast cancer, namely IKKα (CHUK), IKBKB, p50/NFKB1, p65/RELA, NIK (MAP4K4), p52 (NFKB2), RELB, IL-8 (CXCL8), IL6, and MMP-1." (PMID 31602271, 2019). "Moreover, even in nude mouse models, ADV-ApoA1 treatment markedly impeded the lung metastasis of breast cancer cells, indicating that the role of ADV-ApoA1 in inhibiting breast cancer metastasis primarily involves the regulation of the cholesterol/IKBKB/FOXO3a/KRT14 axis." (PMID 38566092, 2024). "Our study demonstrates that cholesterol-mediated cytoplasmic retention of FOXO3a primarily occurs via the IKBKB signaling pathway, rather than the PI3K/Akt or ERK signaling pathways, confirming earlier findings that IKK negatively regulates FOXO3a in breast cancer." (PMID 38566092, 2024).
ovarian carcinoma (37 papers, 2010 to 2025). A malignant neoplasm originating from the surface ovarian epithelium. "This may be confirmed by the fact that, in the case of ovarian cancer, IKBKB expression was upregulated in cases of poor differentiation in histological grade and with the presence of lymph node metastasis." (PMID 39337357, 2024).
colitis (34 papers, 2011 to 2025). Inflammation of the colon. "Moreover, P. candolleana decreased the expression of IKBKB, JUN, CHUK, and TNF-α proteins, thus exerting anti-inflammatory and therapeutic effects on colitis." (PMID 38645561, 2024).
viral infection (30 papers, 2009 to 2025). "Viral infection is one of the most potent stimuli, which trigger the NF-κB pathway through IKBKB activation." (PMID 32423021, 2020). "Importantly, IKBKB has a direct role in the NF-кB signaling pathway which is essential for proinflammatory cytokine production and autophagy during virus infection." (PMID 32423021, 2020). "IKBKB, IFNG and PDGF BB are other proteins that have been shown to be involved in reactive gliosis, inflammation, cellular plasticity, neurogenesis, protection against autoimmune demyelination, and activation of astrocytes, especially during certain viral infections such as HIV-1." (PMID 32225060, 2020).
diabetes (26 papers, 2010 to 2026). "In addition, some proteins, such as inhibitor of nuclear factor kappa B kinase subunit beta (IKKβ), protein kinase C (PKC), and Kelch-like ECH-associated protein 1 (Keap1) that are damaged by redox modifications are responsible for the development of diabetes." (PMID 36014561, 2022).
atherosclerosis (24 papers, 2014 to 2025). A disease characterized by the build-up of fatty material and calcium deposition in the arterial wall resulting in partial or complete occlusion of the arterial lumen. "The targets of ATK2, IKBKB, RAF1, CHUK, TNF, JUN, and PRKCA were mainly involved in fluid shear stress and the atherosclerosis and PI3K-Akt signaling pathways." (PMID 29177114, 2017). "ATK2, IKBKB, RAF1, CHUK, TNF, JUN, and PRKCA were mainly involved in fluid shear stress and the atherosclerosis pathways, pathways in cancer, and the PI3K-Akt signaling pathway." (PMID 29177114, 2017).
glioma (23 papers, 2014 to 2025). A benign or malignant brain and spinal cord tumor that arises from glial cells (astrocytes, oligodendrocytes, ependymal cells). "To demonstrate the application and potential value of this study in clinical glioma, we reported an example biomarker for protein overexpression in glioma, IKBKB." (PMID 37925483, 2023). "The CPTAC data suggested that IKBKB was overexpressed in GBM glioma compared with normal brain tissues." (PMID 37925483, 2023). "To further investigate the overexpression of IKBKB in glioma, we observed the stainings of IKBKB protein in glioma and brain tissues with two different antibodies." (PMID 37925483, 2023). "Computational analysis of immune response and TLR signaling genes led to our main finding of the reduced expression of IKBKB (a gene coding for IKKβ) in high grade gliomas." (PMID 26427514, 2015). "The analysis of merged microarray datasets showed the significantly reduced expression of IKBKB (the gene coding for IKKβ) in high grade gliomas." (PMID 26427514, 2015). "Nevertheless, we hope the finding that the MAPK signaling pathway was overexpressed in glioma with prognostic value can provide novel insight into glioma treatments, and the example drug prediction of the key hub protein IKBKB provided a strategy for future drug discovery." (PMID 37925483, 2023). "But, the RT-qPCR results showed that five genes (IKBKB, PDIA4, RCC2, RPL4, and TXNIP) were low expressed in glioma cell lines compared to HA." (PMID 36111134, 2022). "Down-regulation of the IKBKB expression at the mRNA and protein levels in GBM compared to low grade gliomas has been confirmed in an independent set of tumors." (PMID 26427514, 2015). "IKBKB could be activated by α-KG produced by GDH1 and then upregulate GLUT1 to promote glucose uptake and tumor cell survival, thus accelerating the occurrence of glioma." (PMID 33552118, 2020).
melanoma (21 papers, 2010 to 2024). A malignant, usually aggressive tumor composed of atypical, neoplastic melanocytes. "Conditional suppression of IKBKB inhibits melanoma tumor development in mice, and IKBKB-mediated NFkB activity is required in mutant Hras-initiated tumorigenesis." (PMID 36499305, 2022). "IKBKB is currently undergoing investigation as a therapeutic target in pancreatic carcinoma, lymphoid neoplasms and melanoma." (PMID 35882937, 2022). "IκB kinase β (IKBKB) was identified as a component of NF-κB signaling and is highly active in various malignancies including acute myeloid leukemia, melanoma, breast and pancreatic cancer." (PMID 26993770, 2016). "In addition, selected members of NFKB and NOTCH signaling pathways (IKBKB, NOTCH2, HES1, PRKCA) were strongly overrepresented in CD271+ melanoma-initiating cells." (PMID 31118427, 2019).
glioblastoma (16 papers, 2014 to 2024). The most malignant astrocytic tumor (WHO grade IV). "Down-regulation of IKBKB expression and NFκB signaling in microglia/macrophages infiltrating glioblastoma correlates with defective expression of immune/inflammatory genes and M2 polarization that may result in the global impairment of anti-tumor immune responses in glioblastoma." (PMID 26427514, 2015).
Immunodeficiency (16 papers, 2015 to 2025). Failure of the immune system to protect the body adequately from infection, due to the absence or insufficiency of some component process or substance. "Since T cell defects and deficiency of Tregs are a hallmark of previously reported homozygous IKBKB mutations in patients with severe early-onset immune deficiency, we also examined T cell phenotype and function." (PMID 40529371, 2025). "This panel screens for major monogenic immunodeficiencies, including predominantly antibody deficiencies (e.g., TNFRSF13B/TACI, ICOS, CD19, IKBKB), combined immunodeficiencies, phagocytic and innate immunity defects, and complement pathway deficiencies." (PMID 40918823, 2025). "Heterozygous GoF mutations in IKBKB (encoding IKK2) result in combined immune deficiency, while homozygous LoF results in severe combined immune deficiency." (PMID 38528069, 2024). "IKBKB deficiency is a rare and special immunophenotype of severe immunodeficiency, which presents in neonates as persistent respiratory or gastrointestinal viral, bacterial, or fungal infections, often associated with protracted diarrhea and failure to thrive." (PMID 33658989, 2020). "Mutations in the IKBKB gene cause severe immunodeficiency, characterized clinically by persistent respiratory or gastrointestinal infections." (PMID 33658989, 2020). "Similarly, nonsense mutations in IKBKB caused a paucity in Treg cell numbers in four infants along with combined immunodeficiency." (PMID 35672519, 2022). "Heterologous IKZF mutation in B cell deficiency and autoimmunity, heterologous TNFAIP3 mutation in autoinflammation and immunodeficiency, heterologous IKBKB variant in common variable immunodeficiency, and homozygous TNFSF13 (APRIL) deficiency in plasmacyte defect were reported in the past 5 years." (PMID 33766139, 2021). "One of the more frequently reported immunodeficiencies in FN children in our survey was IKBKB combined immunodeficiency." (PMID 40061245, 2025). "We present immunological and genetic analysis of a Tunisian patient with two homozygous variants of uncertain significance (VUSs) in the IKBKB and AICDA genes, suspected of causing hyper-IgM and immune deficiency." (PMID 40529371, 2025). "In this article, we provide a comprehensive immunological and genetic study of a patient with two homozygous VUSs in the IKBKB and AICDA genes suspected to be responsible for the hyper-IgM and immune deficiency observed in a Tunisian patient treated at Sidra Medicine in Qatar." (PMID 40529371, 2025).
asthma (15 papers, 2010 to 2024).
colon carcinoma (15 papers, 2006 to 2024). "In colon cancer, lower IKBKB and IKBKG protein levels were noted in tumor tissue compared to normal tissue (p < 0.01; 0.036, respectively)." (PMID 39337357, 2024). "For independent SNP associations, we observed associations with IL6 and IKBKB in colon cancer but not rectal cancer." (PMID 21129206, 2010).
colorectal cancer (15 papers, 2010 to 2025). A primary or metastatic malignant neoplasm that affects the colon or rectum. "While the importance of the genes in the inflammation pathway has been well documented, our study is the first to comprehensively examine polymorphisms in either NFKB1 or IKBKB to identify functional polymorphisms associated with colorectal cancer." (PMID 21129206, 2010). "We applied the hapConstructor method to a multilocus investigation of candidate genes involved in pro-inflammatory cytokine IL6 production, IKBKB, IL6, and NFKB1 (16 SNPs total) hypothesized to operate together to alter colorectal cancer risk." (PMID 21129206, 2010).
pancreatic cancer (15 papers, 2013 to 2025). "Several studies have demonstrated a tumor-promoting effect of IKK (encoded by IKBKB) in intestinal, lung, and pancreatic cancer." (PMID 33178587, 2020).
type 2 diabetes (15 papers, 2010 to 2023). "IKBKB gene expression is critical for gene regulation in various signaling pathways, including IKBKB type 2 diabetes and MAPK signaling." (PMID 37367922, 2023).
lung adenocarcinoma (14 papers, 2014 to 2025). A carcinoma that arises from the lung and is characterized by the presence of malignant glandular epithelial cells. "The differential expression of IKBKB in human lung adenocarcinoma cells would affect the apoptosis rate." (PMID 36817123, 2023). "By differential expression analysis and LASSO logistic regression analysis we constructed an 8-gene (IKBKB, LTBR, MIF, PPARD, PPIA, PSME3, S100A6, SEMA4B) based risk score model to predict lymph node metastasis in lung adenocarcinoma." (PMID 34109216, 2021). "The aim of this study is to investigate the differential expression of IKBKB gene in human lung adenocarcinoma cells line A549 and the cisplatin-resistant variant A549/DDP and the mechanisms of cisplain-resistance induced by IKBKB gene." (PMID 24854552, 2014).
rheumatoid arthritis (14 papers, 2008 to 2026). A chronic, systemic autoimmune disorder characterized by inflammation in the synovial membranes and articular surfaces. "Furthermore, in contrast to IKBKB (IKKβ), A20 has been identified as a susceptibility locus for human immune and inflammatory diseases, such as rheumatoid arthritis, type 1 diabetes, coronary artery disease, and Crohn's disease." (PMID 34626855, 2021).
gastric cancer (13 papers, 2017 to 2024). A primary or metastatic malignant neoplasm involving the stomach. "A study found that the IKBKB rs2272736 polymorphism is associated with survival in gastric cancer patients." (PMID 39768951, 2024). "In addition, the IKBKB polymorphism (rs2272736) is known to be associated with poor prognosis in gastric cancer." (PMID 39061149, 2024). "In addition, a retrospective study by Gong and colleagues found an association between the IKBKB polymorphism rs2272736 and gastric cancer." (PMID 39061149, 2024). "There are data showing that IKBKB polymorphisms are associated with survival in gastric cancer." (PMID 39061149, 2024).
lymphoma (13 papers, 2010 to 2026). A malignant (clonal) proliferation of B- lymphocytes or T- lymphocytes which involves the lymph nodes, bone marrow and/or extranodal sites. "NF-kB and its regulatory upstreaming protein inhibitor of nuclear factor kappa B kinase subunit beta (IKBKB) transcription can probably favor lymphoma cell survival by promoting the increase of GLUT proteins on the plasma membrane via AKT." (PMID 29937761, 2018). "We tested this hypothesis in lymphomas because of our prior analysis showing that CYLD, IKBKB (encoding IKKβ), and IKBKG (encoding NEMO) are highly co-expressed in hemato-lymphoid cells." (PMID 32024820, 2020). "Cluster 1 (top right) included genes such as CD79A, PTPRC, EZH2, MMP9, IKBKB, or CASP8, which were upregulated in GCB lymphomas (top right colored in orange)." (PMID 41472741, 2025). "Other genes, such as IKBKB, PTPRC, CASP8, or CD79B, with small p-values did not have a great magnitude of changes between the lymphoma subtypes." (PMID 41472741, 2025).
Sepsis (12 papers, 2013 to 2023). Sepsis is defined as life-threatening organ dysfunction caused by a dysregulated host response to infection. "The four key genes that were identified to have both significant diagnostic and prognostic value in sepsis (IKBKB, PRKCQ, WIPI1, and SH3GLB1) were validated by RT-qPCR in whole blood samples obtained from sepsis patients and healthy controls." (PMID 37701780, 2023). "The results showed that IKBKB and PRKCQ were significantly downregulated in the sepsis group, while SH3GLB1 and WIPI1 were significantly upregulated." (PMID 37701780, 2023). "For sepsis, we noticed several inflammatory and immune-related proteins, such as IRAK1, IRAK3, IKBKB, and STAT3, in the network, suggesting overlap of the inflammatory response activated in COVID-19 and sepsis." (PMID 33156843, 2020).
liver cancer (11 papers, 2010 to 2023). An epithelial or non-epithelial malignant neoplasm that arises from the liver. "HULC also increased p‐P65 and p‐IkBkB levels, thus indicating that it can drive autophagy‐mediated activation of the NF‐kB signaling pathway in liver cancer cells." (PMID 36213936, 2023).
osteosarcoma (9 papers, 2009 to 2023). A usually aggressive malignant bone-forming mesenchymal neoplasm, predominantly affecting adolescents and young adults. "Then we used rescue experiments to verify the impact of MiR-218-5p on the role of circ_0028171 to IKBKB expression and malignant phenotype in osteosarcoma progression." (PMID 33041665, 2020). "Above all, these results illustrated that circ_0028171 took part in the progress of osteosarcoma the increasing expression of IKBKB by competing for miR-218-5p." (PMID 33041665, 2020). "Besides, we also found that IKBKB expression was significantly increased in above 20 paired osteosarcoma cancer tissues compared with surrounding normal tissues." (PMID 33041665, 2020). "Nonetheless, little was known about the fuction of IKBKB in osteosarcoma." (PMID 33041665, 2020). "In addition, our present study revealed that IKBKB expression was significantly upregulated in above 20 paired osteosarcoma cancer tissues compared with adjacent normal tissues." (PMID 33041665, 2020). "Next, we explored whether miR-218-5p regulates osteosarcoma cancer progression through IKBKB." (PMID 33041665, 2020).
psoriasis (9 papers, 2013 to 2025). An autoimmune condition characterized by red, well-delineated plaques with silvery scales that are usually on the extensor surfaces and scalp. "There was significant enrichment of genes controlled by the transcription factors IKBKB (log2fold enrichment 6.361, Padj = 0.040) and STAT1 (log2fold enrichment 3.679, Padj = 0.040) in psoriasis uninvolved skin." (PMID 37137278, 2024). "Overexpression of CHUK, IKBKB, NFKBIA, NFKB1, JAK2, STAT1 and STAT3, as inflammation related factors, was detected in the psoriasis model group." (PMID 34834106, 2021).
Parkinson disease (8 papers, 2017 to 2023). A progressive degenerative disorder of the central nervous system characterized by loss of dopamine producing neurons in the substantia nigra and the presence of Lewy bodies in the substantia nigra and locus coeruleus. "The increased activity of IKBKB is also involved in several neurodegenerative disorders, including HD, Alzheimer’s disease (AD), and Parkinson’s disease (PD)." (PMID 35628660, 2022).